BDNF (brain derived neurotrophic factor)
Diseases named in the same sentence as BDNF in open-access papers (continued):
Sharing a sentence is not in itself a finding about the gene and the disease.
ischemic stroke (continued). "Although, elevated SUMO-conjugated proteins and BDNF levels after an ischemic stroke have been reported in literature, a functional link between BDNF and SUMO pathway has not been reported so far." (PMID 35307349, 2022). "Furthermore, combining ICA and MSCs was shown to promote angiogenesis and neurogenesis, as a result of increased production of VEGF and brain-derived neurotrophic factor (BDNF) through activation of PI3K and Erk1/2 MAPK, in an ischemic stroke rat model." (PMID 32582713, 2020). "For example, neutralising BDNF did not completely abolish the observed improvements in functional deficit following MSC administration in a rat model of ischaemic stroke." (PMID 31964413, 2020). "The active component FA via inhibiting inflammation and increasing the BDNF level might be, in part, responsible for the neuroprotective effects of DCH in ischemic stroke." (PMID 28769792, 2017). "In the present study, genetic variation at the BDNF locus was not a major contributor to ischemic stroke severity, recovery or short-term functional outcome." (PMID 25470006, 2014). "It is noteworthy that BDNF is also produced in non-neuronal cells (such as astrocytes, microglia and endothelial cells) after ischemic stroke, and therefore these cells may contribute significantly to the BDNF-dependent recovery." (PMID 38469139, 2024). "In addition to proteomic alterations, such as tyrosine phosphorylation, in the pathogenesis of ischemic stroke, growth factors or neurotrophic factors, including IGF, FGF, and BDNF, can reduce cell damage by inhibiting the tyrosine kinase receptor-activated apoptosis pathway." (PMID 37009888, 2023). "MSCs and EA treatment could improve the expression levels of trophic factors such as brain-derived neurotrophic factor (BDNF), neurotrophin-4 (NT4), and vascular endothelial growth factor (VEGF) in ischemic stroke, which are all very helpful for brain tissue regeneration." (PMID 35211177, 2022). "In addition, EA may improve synaptic plasticity in rats with ischemic stroke via protecting synaptic ultrastructure and promoting the levels of NGF, BDNF, GAP-43 and p38 in the ischemic brain's cortex." (PMID 30618558, 2018). "Our study suggests that genetic variation in the BDNF region may be related to differences in long-term outcome after ischemic stroke, independent of baseline deficits, etiologic subtype, and traditional cardiovascular risk factors." (PMID 25470006, 2014). "Serum samples from 78 diabetic and non-diabetic patients with ischemic stroke (acute ischemic stroke or transient ischemic attack) revealed a high level of miRNA-195-5p and miRNA-451a at 0, 24, and 72 hours after the stroke event, with low levels of BDNF and VEGF-A at the same time-points." (PMID 35757539, 2022).
autism (133 papers, 2008 to 2026). Persistent deficits in social interaction and communication and interaction as well as a markedly restricted repertoire of activity and interest as well as repetitive patterns of behavior. "There is evidence that NTRK2 gene is a susceptibility factor for autism and a disruption of the BDNF/TrkB signaling pathway is associated with autism." (PMID 41245836, 2025). "The autism-like social behavioral deficits are likely linked to diminished activity-dependent BDNF signaling in PFC." (PMID 37205980, 2023). "In an ASD animal study, many genes and proteins were found to be changed, such as the autism-related susceptibility genes BDNF, Shank3, and ERK1." (PMID 33456456, 2020). "In the case of autism, there are candidate risk genes encoding for calcium channels, calcium-regulated signalling proteins, BDNF, CREB, PI3K and ERK1/245, i.e. some of the genes that were significantly affected by ACR in this study." (PMID 33028897, 2020). "We propose a pathogenic mechanism in autism involving SPRY3 deregulation impacting on the BDNF–TrkB–p75NTR neurotrophin pathway." (PMID 31275178, 2019). "The combination of upregulated BDNF and increased brain size in male ZnT3 null mice suggests the interesting possibility that BDNF upregulation is one of the factors that causes large brains as well as autism phenotypes in these mice." (PMID 27352957, 2016). "Sonic hedgehog (SHH) protein and brain-derived neurotrophic factor (BDNF) are associated with oxidative stress in autism." (PMID 22846252, 2012). "In this study, we applied polyacrylamide gel-based microarray combined with dual-color hybridization for association study of four BDNF polymorphisms with autism." (PMID 19582215, 2009). "In this study, we examined the SNP- and haplotypic-association of BDNF gene with autism in case-control study." (PMID 19582215, 2009). "It is concluded that the polyacrylamide gel-based microarray combined with dual-color hybridization is a rapid, simple and high-throughput method for SNPs genotyping, and has been successfully used for association study of BDNF gene with autism." (PMID 19582215, 2009). "This review summarizes the current evidence on some selected proteins such as tau protein, NFL, and BDNF as well as IGF-1 that appear to be the best protein candidates for better understanding the causes of autism, as well as for use as fluid biomarkers in the diagnosis and monitoring of ASD." (PMID 42280241, 2026). "By using mice with genetic knock-in of this human BDNF methionine (Met) allele, our recent studies have shown that diminished activity-dependent BDNF signaling differentially induces autism-like social deficits in males and females, and that males appear to be more severe than females." (PMID 39569070, 2024). "Additionally, the BDNF Val66Met mutation, which diminishes activity-dependent BDNF signaling, has been associated with autism-like social deficits in mice, with differences between males and females." (PMID 39125882, 2024). "Low neonatal serum BDNF levels have been associated with impaired neurodevelopment, i.e., in cases with neurodevelopmental disorders (e.g., autism), lower BDNF serum levels have been found in umbilical cord serum than in healthy controls." (PMID 37360514, 2023). "A large sample size is required to determine whether the Met allele in the BDNF gene is a genetic marker in humans who are at increased risk for autism and males are more susceptible than females." (PMID 37205980, 2023). "Meta-analyses have uncovered a positive association between autism and high blood BDNF levels." (PMID 37239153, 2023). "With these results, we experimentally showed that social dysfunction in the VPA mouse model of autism might be caused by E/I imbalance stemming from BDNF deficits during the developmental stage." (PMID 35465089, 2022).
autism (continued). "Impairments in BDNF-mediated signaling have also been associated with autism." (PMID 30899214, 2019). "In the present study, and using the VPA-model in Sprague–Dawley rats, we have found autism-like behaviors that were associated with a reduction in BDNF transcripts containing the long-3′UTR in the inferior blade of the DG and in the polymorphic layer of the CA3 region." (PMID 31787877, 2019). "Besides the dysregulation of the immune system, elevated serum levels of BDNF were reported to be associated with autism." (PMID 30127728, 2018). "Finally, we investigated a possible causal link between MMP-9 activation and BDNF upregulation, increased brain size, and autism phenotypes in ZnT3 null mice." (PMID 27352957, 2016). "BDNF is trophic for serotonergic neurons, a finding that may be associated with abnormal serotonin levels found in autism." (PMID 26866045, 2015). "We hypothesize that, although both up- and down-regulation of BDNF may induce autism symptoms, only BDNF up-regulation is associated with the hyperconnectivity and large brain size observed in most young idiopathic ASD patients." (PMID 25182223, 2014). "A genetic association among autism and the TrkB gene, abnormal blood BDNF levels in children with autism, and increased BDNF protein expression in postmortem brain tissue of autistic individuals suggests that BDNF/TrkB signaling plays a role in the pathophysiology of autism." (PMID 24904293, 2014). "However, further studies including replication of these findings in a large sample, the association of polymorphisms with BDNF expression and the functional impact of BDNF in autism are warranted." (PMID 19582215, 2009). "Furthermore, BDNF hyperactivity may be associated with early brain outgrowth, increase in the prevalence of seizures in autism, and similar behaviors observed in autism and fragile X syndrome." (PMID 25530675, 2014). "BDNF has been studied in relation to autism, as it plays a crucial role in neuronal development and plasticity." (PMID 40469240, 2025). "Training has been suggested to have an impact on autism through mechanisms such as increased BDNF and decreased Bax expression." (PMID 40652064, 2025). "By using mice with genetic knock-in of this human BDNF methionine (Met) allele, our previous studies have shown differential severity of autism-like social deficits in male and female BDNF+/Met mice." (PMID 39569070, 2024). "Brain-derived neurotrophic factor (BDNF) gene haploinsufficiency has been implicated in childhood-onset obesity, intellectual disability, and autism." (PMID 38397265, 2024). "Heterozygous D2+/− knockout mice exposed to early postnatal stress develop symptoms similar to those in autism; this problem is accompanied by BDNF and TrkB underexpression in the dorsal striatum." (PMID 37239153, 2023). "We have provided the first pre-clinical evidence that diminished activity-dependent BDNF signaling induced autism-like behavioral deficits in both sexes, which supports that diminished activity-dependent neural signaling is a common molecular pathway in ASD." (PMID 37205980, 2023). "The potential therapeutic effects of acupuncture-induced activation of brain-derived neurotrophic factor in the treatment of autism have also been demonstrated." (PMID 38213582, 2023). "There was a significantly lower social preference index in male than in female BDNF+/Met mice, which suggests diminished activity-dependent BDNF signaling sexually differentially affects the severity of autism-like social deficits." (PMID 37205980, 2023). "Compelling data suggest that microglial activation as well as decreased CREB/BDNF to be important activators for oxidative stress and inflammatory cytokines in AD, autism, and neurodegenerative disease, leading to cognitive and learning impairment." (PMID 36943623, 2023).
autism (continued). "The autism-like social deficits and self-grooming were more severe in male BDNF+/Met mice, which is consistent with the prevalence of ASD being higher in males than in females, at a about 4: 1 ratio." (PMID 37205980, 2023). "The significant higher time engaged in self-grooming in male BDNF+/Met mice than female BDNF+/Met mice indicates the autism-like repetitive and restrictive behaviors in males are more severe than those of in females." (PMID 37205980, 2023). "Growth factors: A fascinating feature of autism is that there are elevated levels of growth factors in the brain, for example brain-derived neurotrophic factor (BDNF) in both the cortex and hippocampus, and in blood sera." (PMID 36412693, 2022). "PPA-induced autism-like rats administered with MgB (at all doses) exhibited a significant increase in the expression levels of BDNF, GAP, ICAM, PSD-93, and PSD-95 in the brain and decreased GFAP expression, compared to the control group." (PMID 35334937, 2022). "Based on our search and other reports, a growing number of studies have focused on the link between BDNF and autism." (PMID 35465089, 2022). "Here, we studied the therapeutic effect of FUS combined with BDNF plasmid-loaded cationic microbubbles (BDNFp-CMBs) in a rat model of autism." (PMID 36117626, 2022). "So, it would be appropriate to measure brain acetylcholine, GABA, dopamine, serotonin levels and correlate the same to the levels of BDNF, and decipher the relationship between various neurotransmitters and the development of autism in our later studies." (PMID 35465089, 2022). "Treatment with exogenous BDNF during the critical E/I imbalance period rescued synaptic functions and autism-like behaviors, such as social defects." (PMID 35465089, 2022). "BDNF plays an important role in treating autism, but BDNF cannot pass through the BBB; thus, intravenous infusion of BDNF cannot effectively reach PFC neurons to exert biological effects." (PMID 36117626, 2022). "In this VPA-induced autism model, the complex mechanism by which BDNF regulates excitatory synapses and inhibitory synapses should be explored in further studies." (PMID 35465089, 2022). "More studies should closely examine the role BDNF plays in the etiology of autism and the relevance of its increased levels in the serum to its function in the brain." (PMID 34439657, 2021). "Studies of animal models of autism have reported increased BDNF protein and mRNA levels in fetal brains." (PMID 34439657, 2021). "Administration of β-carotene, the precursor of retinoic acid, in an autism mouse model increased BDNF concentration." (PMID 33758244, 2021). "The objective of the present study was to analyze BDNF serum concentration levels in children with classic forms autism and a healthy control group to determine if there is a correlation between ASD and BDNF serum levels." (PMID 33060610, 2020). "The prenatal VPA-model of autism also shows disparities in BDNF protein levels, i.e., they increase in the hippocampus, but decrease in the cortex." (PMID 31787877, 2019). "It would therefore be intriguing to examine the ‘rubber tail illusion’ in mouse models of autism that have impaired BDNF-related function in the cerebral cortex." (PMID 31101876, 2019). "In the VPA-treated rats, which showed autism-like behavior, we found reduced levels of BDNF mRNA (especially L-bdnf) in the dentate gyrus (DG) and CA3 areas." (PMID 31787877, 2019). "Low doses but extended prenatal VPA treatment (from E7 to E18), that also trigger autism-like behaviors, produced an increase of BDNF levels in the hippocampus of PN30 Wistar rats, as detected by Elisa assay." (PMID 31787877, 2019). "Diverse evidences indicate that different types of autism present disturbances in neuronal development and synaptic plasticity, probably due to a dysfunction of neurotrophic factors, particularly BDNF." (PMID 31787877, 2019).
autism (continued). "In order to contribute to this topic, we treated prenatal rats with Valproate, a well-validated model of autism, to analyze BDNF levels in the hippocampus of juvenile rats." (PMID 31787877, 2019). "BDNF, a well-known neurotrophin fundamental for brain development and function, has also been shown to be highly expressed in autism." (PMID 30975733, 2019). "ISH experiments conducted with BTBR T+tf/J (BTBR) mice, an inbred strain model of autism, revealed a specific reduction of BDNF mRNA, reaching 73% in DG and 65% in CA3." (PMID 31787877, 2019). "Levels of BDNF in serum and plasma are higher among subjects with autism than in matched controls, by four meta-analyses of overlapping datasets." (PMID 31548888, 2019). "Western blotting further revealed that increased BDNF-immunoreactivity in ASD is not due to increased mature BDNF or to changes in BDNF mRNA levels, but that individuals with autism had greater levels of pro-BDNF and less truncated BDNF compared to controls." (PMID 29691724, 2018). "High expression of BDNF is also found in a model of autism [valproic acid (VPA)-treated rat offspring]." (PMID 28751869, 2017). "Katoh-Semba, Wakako found lower BDNF levels in the serum of subjects with autism as compared to age matched healthy control subjects." (PMID 26866045, 2015). "Baseline serum BDNF concentration was determined for comparison to clinical ratings using an autism severity measure and the Pervasive Developmental Disorder-Behavior Inventory (PDD-BI)." (PMID 26866045, 2015). "Higher levels of serum BDNF are consistent with the observations of an increase of the number of neurons in the prefrontal cortex of autistic disorder patients." (PMID 26866045, 2015). "Other studies have shown higher concentrations of serum BDNF in older children (ages 3 to 27) with autistic disorders as well as higher BDNF levels in the basal forebrain in adults with AD compared to healthy controls." (PMID 26866045, 2015). "Because of its wide range of actions and presence in multiple brain regions and neuronal cell types, levels of BDNF have been studied in a multitude of mental illnesses including mood disorders, psychosis, eating disorders, and autism." (PMID 26866045, 2015). "There is also evidence supporting dysregulation of upstream activators of the ERK1/2 and mTOR pathways in autism, including BDNF signaling through the TrkB receptor (Maija Castrén and Castrén, 2014)." (PMID 26483618, 2015). "Nonetheless, we found that the protein levels of both pro-BDNF and BDNF and mRNA level of BDNF were decreased in autism sera treated rat brain tissue." (PMID 25769033, 2015). "In this small exploratory study we assessed the role of gender, AD symptom characteristics, and severity in relation to BDNF levels in children with autistic disorder." (PMID 26866045, 2015). "P6 treatment significantly enhanced BDNF mRNA levels (autism serum vs. autism serum+P6 group, Bonferroni’s post-hoc test, p>0.05, Student’s t-test, p = 0.0049)." (PMID 25769033, 2015). "Increasing evidence suggests a direct or indirect involvement of BDNF in autism, and this factor plays a key role in neuronal survival, morphology, differentiation and synaptic strength." (PMID 26061495, 2015). "Brain Derived Neurotrophic Factor (BDNF) is an excellent example of a growth factor that is widely used throughout the central nervous system and the gene is also present within the core autism list studied here." (PMID 25477785, 2014). "The findings of increasing serum and brain tissue BDNF levels are presented in autism relative to normal controls." (PMID 25530675, 2014). "This study also showed that BDNF levels were significantly increased in children with autism relative to that in controls, supporting a role of NTRK2/BDNF signaling as a susceptibility factor for the disorder." (PMID 23697635, 2013).